BRCA1 (BRCA1 DNA repair associated)
Diseases named in the same sentence as BRCA1 in open-access papers (continued):
Sharing a sentence is not in itself a finding about the gene and the disease.
ovarian carcinoma (continued). "Mutations in the BRCA1, BRCA2, and MMR genes can increase the risk of ovarian cancer from 1.6% to 40%, 18%, and 10%, respectively." (PMID 37304283, 2023). "International guidelines recommend RRSO after completion of childbearing or at 35–40 years of age for BRCA1 mutations carriers or at 40–55 years of age for BRCA2 mutation carriers to reduce the risk of breast and ovarian cancers." (PMID 36614207, 2023). "While the association of BRCA1 and BRCA2 PV with breast and ovarian cancer risks is well-defined, the potential association of these variants with other cancers is not so well established." (PMID 38067403, 2023). "To do so, we tested the combination of PRT543 with olaparib in an ovarian cancer PDX model (CTG-0703, BRCA1 mutated)." (PMID 37861290, 2023). "More specifically, women having mutations in BRCA1 and BRCA2 are thought to have elevated risk for the development of ovarian cancer." (PMID 36903316, 2023). "Clinically, BRCA mutations have been simply regarded as HR defects, and BRCA1- and BRCA2-mutated ovarian cancers have been treated as the same disease." (PMID 38017453, 2023). "For ovarian cancer, the risk is roughly 20 times higher for BRCA2 and 40 times higher for BRCA1 pathogenic variant carriers." (PMID 37185387, 2023). "Cancers with BRCA1/2 mutations including TNBC and ovarian cancer demonstrate sensitivity to PLK1 inhibitors like onvansertib." (PMID 38234395, 2023). "Some international recommendations suggest that BRCA1/2 genetic testing should be offered for all newly diagnosed epithelial ovarian cancer, along with HRD assessment." (PMID 38069422, 2023). "In this study, we aimed to identify the prevalence of the BRCA1 c.-107A > T SNV in breast or ovarian cancer patients with tumor BRCA1 promoter hypermethylation." (PMID 36112334, 2023). "Approximately 11% of ovarian cancer cases have hypermethylation at the BRCA1 gene’s promoter level, whereas only 3% of cases have it at the RAD51C gene level." (PMID 37296748, 2023). "We selected all breast and ovarian cancer cases that tested positive for tumor BRCA1 promoter hypermethylation at the Netherlands Cancer Institute and Sanger sequenced the specific mutation in the tumor DNA." (PMID 36112334, 2023). "Moreover, germline mutations in the breast cancer susceptibility gene 1 (BRCA1) considerably increase the risk of breast and ovarian cancers and, thus, modulation of PTEN/BRCA1 proteins may prove therapeutically beneficial for breast, ovarian, and prostate cancer treatment." (PMID 36903626, 2023). "BRCA1 is a nuclear protein and is reportedly localized in the cytoplasm in breast and ovarian cancer cells." (PMID 36702632, 2023). "One study reported that relatives of BRCA1 and BRCA2 carriers have an increased risk for breast and ovarian cancers, and relatives of BRCA2 carriers also have an increased risk for pancreatic cancer." (PMID 36861435, 2023). "BRCA1 or BRCA2 mutation carriers show a lifetime risk of up to approximately 85% and 20%–40% for breast and ovarian cancers, respectively." (PMID 37644384, 2023). "The process of HR includes several mediator genes including BRCA1 and BRCA2; however, these are also among the most mutated HR genes and commonly present in ovarian cancer." (PMID 36900195, 2023). "Germline pathogenic variants (PVs) in the BRCA1 and BRCA2 genes are the most frequent cause of hereditary breast and ovarian cancers." (PMID 38053165, 2023). "Heterozygous germline mutation in the BRCA1 gene confers a 60% lifetime risk of breast or ovarian cancer, whereas BRCA2 mutations are associated with a risk of breast or ovarian cancer of 55% and 15%, respectively." (PMID 37415740, 2023).
ovarian carcinoma (continued). "Among them, BRCA1 and BRCA2 were the first genes reported to be associated with an increased risk of breast and ovarian cancer." (PMID 37566130, 2023). "Germline genetic alterations affecting BRCA1/2 are primarily responsible for breast and ovarian cancer." (PMID 38201484, 2023). "Among the patients with epithelial ovarian cancer (n = 27), most presented with high-grade serous carcinoma (n = 20, 74.1%) and stage III–IV disease (n = 25, 92.6%), and eight (29.6%) had BRCA1/2 mutation." (PMID 37993659, 2023). "In total, 0.5% of all individuals had a BRCA1/2 AJ founder variant, while 7.7% had PLPV in a high-risk breast/ovarian cancer gene." (PMID 37535880, 2023). "Patients with ovarian cancer and TNBC are also more likely to have mutations in BRCA1 than BRCA2, while, the opposite is true for patients with ER + BC." (PMID 37589839, 2023). "For instance, it has been shown that genetic testing in Slovenian patients with breast and ovarian cancer consistently yields very high BRCA1 and BRCA2 detection rates compared to patients from other populations." (PMID 37002323, 2023). "Patients with germline BRCA1 or BRCA2 mutations account for about only 15% of all patients with ovarian cancer, but approximately 50% of epithelial ovarian cancers harbor defects in HRR." (PMID 37457127, 2023). "The cumulative risk of developing ovarian cancer has been reported as 39–44% for BRCA1 mutations and 11–17% for BRCA2 mutations, compared to a cumulative risk of ovarian cancer in the general population of 1–2%." (PMID 37957733, 2023). "For example, when hereditary breast and ovarian cancer is suspected, testing for the BRCA1/BRCA2 genes is used effectively in clinical practice." (PMID 38201513, 2023). "In contrast to the general population, ovarian cancer in BRCA mutation carriers is diagnosed at an earlier median age (54 and 59.5 years for the BRCA1 and BRCA2 mutations, respectively, vs. 63 years for wild-type BRCA)." (PMID 36835955, 2023). "This review offers an overview of BRCA1’s molecular role as a tumor suppressor focusing on breast and ovarian cancers." (PMID 37762577, 2023). "Among Greek patients with breast and ovarian cancer, BRCA1 and BRCA2 LGRs alone comprise up to 24% of pathogenic variants identified in BRCA1 and BRCA2." (PMID 38067228, 2023). "At the same time, induction of hypoxia via inhibition of VEGF is associated with downregulation BRCA1/2 and RAD51, in BRCA1/2 wild-type ovarian cancer cell lines." (PMID 37430137, 2023). "About 5–10% of all ovarian cancer cases are familial, and about 15–25% of hereditary ovarian cancer (HOC) cases are mediated by high-penetrance mutations in the BRCA1 and BRCA2 genes." (PMID 37013556, 2023). "Risk factors for ovarian cancer include smoking, menopause, hormone replacement therapy (HRT), endometriosis, and BRCA1 and 2 mutations." (PMID 36672978, 2023). "Generally, carriers of BRCA1 and BRCA2 mutations have an increased risk (71.4-87% for the BRCA1 mutation and 77-88% for the BRCA2 mutation) of developing breast and ovarian cancers." (PMID 37719058, 2023). "All 10 patients were treated with camonsertib at ≥120 mg QD (3/4 schedule); five achieved clinical benefit and one with ovarian cancer harboring a BRCA1 reversion had a RECIST 1.1 cPR." (PMID 37277454, 2023). "Female relatives of BRCA1 and BRCA2 carriers are at increased risk for breast and ovarian cancers, and male relatives of BRCA2 carriers are at increased risk for pancreatic and prostate cancers." (PMID 36861435, 2023). "Another study reported the silence of the DNA repair gene (BRCA1) in breast and ovarian cancers due to its hypermethylation." (PMID 37893440, 2023).
ovarian carcinoma (continued). "Women who have inherited mutations in the BRCA1 or BRCA2 genes (BRCA-1/2) have substantially elevated lifetime risks for developing breast (80–90% lifetime risk) and/or ovarian cancer (18–40% lifetime risk)." (PMID 37365514, 2023). "Furtherly, this study also evaluates the proportion of HRD status in Chinese ovarian cancer patients, the correlation between HRD scores and BRCA1/2 mutations, and its correlation with the efficacy of platinum-containing chemotherapy." (PMID 36922847, 2023). "Women with a BRCA1/2 germline pathogenic variant (GPV) have an increased risk to develop breast and ovarian cancer." (PMID 37046756, 2023). "BRCA1-mutated, HR-deficient breast or ovarian cancer cells are sensitive to poly(ADP-ribose) polymerase (PARP) inhibitors, and resistance to PARP inhibitors in BRCA1-mutated cells is induced by restoration of HR, which is triggered by REV7 depletion." (PMID 36980607, 2023). "While it is widely accepted that the loss of the second allele is a prerequisite for carcinogenicity in breast cancer and ovarian cancer, BRCA1 haploinsufficient cells show functional deficits under challenging conditions, such as replicative stress." (PMID 38139386, 2023). "Among women with family history of breast and/or ovarian cancer, Black women were less likely to undergo BRCA1/2 testing than White women." (PMID 37626335, 2023). "Similar to BRCA1, a secondary mutation in BRCA2 has also been shown to restore the mutant BRCA2 reading frame into the wild-type reading frame in cisplatin-resistant ovarian cancer." (PMID 37110218, 2023). "A separate JAVELIN PARP Phase I/II trial tested the combination of avelumab and talazoparib in patients with various advanced solid tumors including the BRCA1/2 mutant ovarian cancers." (PMID 37035242, 2023). "One example that illustrates how a predictive test with a low AUC can still be effective is the BRCA1 test for breast and ovarian cancer." (PMID 36981032, 2023). "BRCA1 and BRCA2 mutations are responsible for most hereditary epithelial ovarian cancer, while Lynch syndrome is associated with clear-cell and endometrioid tumors." (PMID 36984544, 2023). "Among clinical responders with known allelic status, 78% (7/9) had biallelic LOF, including two patients with germline BRCA1-altered ovarian cancer previously treated with PARPi and platinum therapy." (PMID 37277454, 2023). "To confirm our finding in a BRCA1-mutated ovarian cancer line, we knocked down ZNF251 in the Ovcar8 cell line, a human ovarian cancer line with BRCA1 mutation, and tested their response to multiple PARPis." (PMID 37066268, 2023). "We also looked at the expression and clinical significance of miR-155-5p in WBCs from BRCA1-methylated breast and ovarian cancer patients, as well as cancer-free BRCA1-methylation female carriers." (PMID 37240365, 2023). "The first PARP inhibitor to receive regulatory approval from the FDA was Olaparib in 2014, for the treatment of advanced‐stage BRCA1/2‐mutant ovarian cancers refractory to ≥ 3 prior lines of therapy." (PMID 35834102, 2022). "Germline mutations in the BRCA1 and BRCA2 genes correlate in the development of most cases of hereditary breast and ovarian cancer." (PMID 36556118, 2022). "One of the six patients with pancreas cancer, a BRCA1 carrier, also had a prior history of both breast and ovarian cancer." (PMID 36418296, 2022). "Genetic testing of 1,342 ovarian cancer patients revealed that 176 patients had BRCA gene mutations, including 107 BRCA1 mutations and 67 BRCA2 mutations, and two mutations in both genes, accounting for 13.3% of the comprehensive mutation frequency." (PMID 36685881, 2022).
ovarian carcinoma (continued). "One prominent example is the upregulated NDD in BRCA1 or BRCA2-deficient breast and ovarian cancers (referred to as a deficiency in fork protection)." (PMID 36710880, 2022). "BRCA1 and BRCA2 were shown to be susceptibility genes for ovarian cancer, and the BRIP1, RAD51C, rad51D and mismatch repair genes also play a role in this disease." (PMID 35910206, 2022). "Due to the limited knowledge about the molecular etiology of ovarian cancer, if only the BRCA1/2 gene is tested, more than 5% of patients with deleterious variants in other known risk genes will be missed." (PMID 36729997, 2022). "From their genetic KO screen, they identified Dynein light chain 1 (DYNLL1) loss as a major driver of platinum resistance and of PARP inhibitor resistance in BRCA1 null ovarian cancer cell lines." (PMID 35834102, 2022). "Several inherited cancer-associated BRCA1 mutations have been found within the RING domain and BRCT domains, which indicates that both domains are involved in the suppression of breast and ovarian cancer." (PMID 35805026, 2022). "Our study reveals that BRCAness defects are commonly present in multiple cancer types as BRCA1/2 defects in breast and ovarian cancer." (PMID 36497135, 2022). "In a synthetic lethal interaction, the targeted therapy of BRCA1/2-mutant ovarian cancer has been achieved using PARP inhibitors, since these tumors are deficient for the repair of dsDNA breaks by HR repair pathways." (PMID 35736348, 2022). "This study is the first comprehensive bibliometric analysis of the top 100 most cited papers on BRCA1 and BRCA2 associated breast and ovarian cancer globally." (PMID 36197199, 2022). "BRCA1 is a well-studied tumor suppressor gene and has known implications in breast and ovarian cancers." (PMID 36371461, 2022). "Overall survival was better during the first six years after epithelial ovarian cancer for BRCA1 (HR 0.7, 95% CI 0.58–0.84) and BRCA2 (HR 0.41, 95% CI 0.29–0.59) patients." (PMID 36137114, 2022). "It was previously reported that JQ1 synergized with olaparib in BRCA1/2 wild-type ovarian cancer both in vitro and in vivo and correlated with the suppression of TOPBP1 and WEE1." (PMID 36139634, 2022). "BRCA1 and BRCA2 inherited gene mutations, which greatly increase the risk of developing breast and ovarian cancers, are mutations that are frequently observed in hereditary breast and ovarian cancers (HBOC)." (PMID 35205313, 2022). "Most information on BRCA1 and BRCA2 mutations is tailored to women due to the availability of effective surgical risk reduction procedures for women’s breast and ovarian cancer." (PMID 35303741, 2022). "Next, we applied BRCA1 siRNAs to ovarian cancer cells and then performed CCK8, colony formation, EdU incorporation and apoptosis assays." (PMID 36703740, 2022). "In some cases, tumors exploited NMD by positively selecting for nonsense mutations to downregulate tumor suppressor genes, as has been shown for BRCA1 and BRCA2, which were associated with inherited susceptibility and platinum resistance in ovarian cancer." (PMID 37223641, 2022). "Treatment of ovarian cancer with poly(ADP-ribose) polymerase inhibitors (PARPi) has resulted in improved survival for individuals with a germline or somatic PV in BRCA1/2." (PMID 35418215, 2022). "Taken together, these results display discordant behavior of BRCA1/2m between patients with breast or ovarian cancer, suggesting possible tumor-intrinsic properties of ovarian cancers that combine with the presence of BRCA1/2m to lead to longer survival." (PMID 35909902, 2022). "Using BRCA1/BRCA2 mutated breast and ovarian cancer as the control, we observed that BRCAness is widely present in multiple cancer types." (PMID 36497135, 2022). "Using the transcriptome data, we analyzed the correlation in mRNA expression levels of the BRCA1 gene and genes related to DNA damage response among the ovarian cancer patients." (PMID 35517499, 2022).
ovarian carcinoma (continued). "Our study also showed that the total number of mutations, when considered as a whole, contributed positively to the long-term survival of ovarian cancer patients, which is consistent with previous studies including only BRCA1 or BRCA2 mutant cases." (PMID 35571616, 2022). "Extending the efficacy of PARPi to BRCA1/2 wild-type HR proficient ovarian cancer patients is an unmet clinical need." (PMID 36539830, 2022). "These DSBs can be repaired in normal cells with proficient HRR; however, DSBs cannot be efficiently repaired in BRCA1- or BRCA2-mutated breast and ovarian cancer cells due to HRR deficiency (HRD)." (PMID 35328658, 2022). "Our results advanced the current understanding by showing that downregulating of PKM2 affected the expression of the HR-related proteins ATM, γH2AX and BRCA1 in ovarian cancer cells." (PMID 35280680, 2022). "In contrast, another approach for driving de novo resistance was the knockdown of 53BP1 in BRCA1-mutant ovarian cancer cells, namely the UWB1.289 cell derivatives UWB1.289/53BP1−/− cells." (PMID 36253861, 2022). "Abkevich and colleagues discovered that LOH of intermediate lengths (>15 Mb, but less than the entire chromosome) were significantly associated with HRD, defined as a deficiency in BRCA1/2 (p = 10−11) or RAD51C (p = 0.0003), in ovarian cancer." (PMID 36077694, 2022). "These are the first reports of low-level BRCA1 constitutional mosaicism in patients with ovarian cancer." (PMID 36068545, 2022). "While ovarian cancers in BRCA1/2 carriers generally develop in the 4th or 5th decades of life, evidence suggests that risk of ovarian cancer begins to increase at age 35 for BRCA1 and age 40 for BRCA2." (PMID 35768821, 2022). "Since mutations in BRCA1 and BRCA2 were identified as major causes of ovarian cancer, the relationship between XBP1 and BRAC1/BRAC2 was individually analyzed." (PMID 35991556, 2022). "A BSO is performed between the ages of 35 and 40 in BRCA1 carriers and 40 and 45 in BRCA2 carriers due to the late onset and can reduce the risk of ovarian cancer by 96%." (PMID 35805770, 2022). "Germline mutations of BRCA1 and/or BRCA/2 are present in approximately 14.1% of all ovarian cancer cases." (PMID 36209184, 2022). "While the role of BRCA1/2 genes in familial breast and ovarian cancer is well established, their implication in the sporadic form of both cancers is still controversial." (PMID 35986351, 2022). "This has potential translational significance, as HRR deficiency (HRD) is targetable with PARP inhibitors to exploit synthetic lethality, as is the case with BRCA1/2 ovarian cancer." (PMID 35740599, 2022). "A BRCA1 mutation was found in 3, and BRCA2 in 1 of 31 (together − 12.9%) women diagnosed with ovarian cancer at or under the age of 50 compared to 8 BRCA1 and 6 BRCA2 carriers of 127 (together − 11.0%) women diagnosed at a later age." (PMID 35382848, 2022). "In Tumor-First, universal BRCA1/2-PV tumour testing in all new epithelial ovarian cancer patients is performed (instead of only testing women who request referral)." (PMID 34997316, 2022). "For instance, BRCA1 promoter methylation is an important somatic driver in high grade serious ovarian carcinoma." (PMID 35785170, 2022). "Women with disease-causing gene changes (faults/mutations) in BRCA1, BRCA2, PALB2, CHEK2 and ATM are at an increased risk of developing certain types of cancer—specifically breast (all genes) and epithelial ovarian cancer (only BRCA1, BRCA2, PALB2)." (PMID 35681696, 2022). "At this time, the addition of the PARPi olaparib as maintenance treatment after response to first-line chemotherapy was restricted to patients with BRCA1/2-mutant advanced ovarian cancer." (PMID 36338759, 2022). "The prevalence analysis of BRCA1 and BRCA2 LGRs across multiple cancers revealed that BRCA1 LGR more frequently occurred in ovarian cancer (1.31%, 33/2526), and BRCA2 LGR was more commonly seen in cholangiocarcinoma (0.47%, 2/425)." (PMID 36147908, 2022).